TAP2 (transporter 2, ATP binding cassette subfamily B member)
Diseases named in the same sentence as TAP2 in open-access papers (continued):
Sharing a sentence is not in itself a finding about the gene and the disease.
lung carcinoma (7 papers, 2012 to 2025). "Collectively, these results reveal the potential for increasing or restoring TAP2 expression in human lung cancer cells and suggest the possibility to repurpose available pharmacologic agents to treat patients with TAP2-deficient NSCLC." (PMID 40091029, 2025). "We also recognize IL-4 produced in the tumor microenvironment as the causative signal mediating the epigenetic TAP2 silencing in lung cancer." (PMID 40091029, 2025). "Available pharmacologic agents can increase TAP2 expression in lung cancer cells and could potentially be tested in therapeutic clinical trials alone or in combination with other agents to treat patients with TAP2-deficient malignancies." (PMID 40091029, 2025). "It is envisioned that IL-4 signaling can also induce effects beyond TAP2 downregulation in lung cancer cells." (PMID 40091029, 2025). "Together, these results show that TAP2 expression can modify key intracellular signaling pathways and limit the response to proinflammatory cytokines in lung cancer cells." (PMID 40091029, 2025). "Epigenetic modulators and other drugs with known anti-cancer activity increased TAP2 expression and its function in lung cancer cells." (PMID 40091029, 2025). "Together, these results indicate that TAP2 downregulation limits the levels of surface HLA class-I antigens in lung cancer cells under both control and proinflammatory-like conditions." (PMID 40091029, 2025). "Collectively, these results reveal that IL-4 reduces TAP2 expression, mimics the effects of TAP2 downregulation and mediates adaptive immune evasion of human lung cancer cells." (PMID 40091029, 2025). "Downregulation of TAP1 and/or TAP2 in lung cancer cells, resulting in resistance to TCR-dependent lysis." (PMID 38067336, 2023). "Our earlier studies have stressed downregulation of TAP1 and/or TAP2 in lung cancer cells, resulting in resistance to TCR-dependent lysis." (PMID 31333652, 2019). "Interestingly, our transcriptomic analysis revealed that TAP1 expression is reduced after TAP2 silencing in lung cancer cells, and TAP2 is also reduced after TAP1 downregulation, supporting interdependency in the expression of these proteins." (PMID 40091029, 2025). "Finally, we perform pharmacologic screens to uncover strategies to revert TAP2 downregulation in lung cancer cells and re-sensitize tumors to T-cell recognition and elimination." (PMID 40091029, 2025). "Silencing of TAP2 in lung cancer cells altered key intracellular immunomodulatory pathways, limited sensitivity to proinflammatory cytokines, reduced the levels of surface peptide-HLA complexes and protected malignant cells from tumor antigen-specific T-cell killing via SOCS1 upregulation." (PMID 40091029, 2025). "In addition, exposure of lung cancer cells to IL-4 suppressed the increase in TAP2 protein induced by IFNγ or IFNγ + TNFα." (PMID 40091029, 2025). "Moreover, low TAP1/TAP2 expression led to the overexpression and efficient presentation of the antigen preprocalcitonin in lung carcinoma, as recognized via tumor-specific cytotoxic T lymphocytes." (PMID 35837087, 2022). "Comparable responses in TAP2, SOCS1 levels and surface peptide-HLA complexes after IL-4 treatment were observed in PC9 lung cancer cells." (PMID 40091029, 2025). "SOCS1 protein was also significantly higher in A549 cells after TAP2 downregulation and the expression of TAP2 reduced SOCS1 protein levels in lung cancer cells supporting a bi-directional modulation." (PMID 40091029, 2025). "TAP deficiencies have been observed in a wide variety of human cancers, including cervical carcinoma, head and neck carcinoma, melanoma, gastric cancer, and lung cancer, with up to 70% of NSCLC expressing low levels of TAP1 and/or TAP2." (PMID 38067336, 2023). "We therefore evaluated the prevalence of TAP downregulation in human lung cancer specimens by analysing the expression levels of TAP1 and TAP2 mRNA in primary human tumours and autologous normal lungs." (PMID 30504837, 2018).
lung carcinoma (continued). "Consistent with an epigenetic mechanism mediating TAP2 reduction in lung cancer cells, we identified 4 HDAC inhibitors able to increase TAP2 expression without increasing PD-L1 expression." (PMID 40091029, 2025). "There was a human lung cancer cell line (LCD) with negative expression for every component except for TAP2; expression of TE8 was increased in TAP2 compared with LCD." (PMID 22134332, 2012).
breast carcinoma (6 papers, 2016 to 2022). "The present study investigated the levels of TAP1 and TAP2 in 480 breast cancer specimens representing 160 patients with breast cancer." (PMID 29091951, 2017). "We showed that higher levels of TAP1 and TAP2 were present in high-grade breast carcinoma and that TAP1 was expressed at higher levels in stage 2 tumors than in stage 1 tumors." (PMID 29091951, 2017). "Both TAP1 and TAP2 immunohistochemical expression levels correlated significantly with breast cancer characteristics (P < .001)." (PMID 29091951, 2017). "The expression levels of TAP1 and TAP2, as measured by the quick score, were positively correlated in breast cancer specimens." (PMID 29091951, 2017). "Our study is the first to utilize TMAs to examine TAP1 and TAP2 levels of 480 breast cancer specimens from 160 female patients with breast cancer." (PMID 29091951, 2017). "Our study has shown the opposite, with TAP1 and TAP2 being expressed at lower levels in early stages of breast cancer." (PMID 29091951, 2017). "The results of this study contradict a previously published report investigating TAP1 and TAP2 levels in 53 patients with breast carcinoma, as well as a report investigating TAP1 levels in primary vs metastatic breast cancer." (PMID 29091951, 2017). "In this study, we investigated the immunohistochemical expression of TAP1 and TAP2 in 160 patients with breast cancer and correlated their expression levels with clinicopathologic parameters." (PMID 29091951, 2017). "We have seen high protein levels of both TAP1 and TAP2 in high grade breast cancer before." (PMID 34047812, 2021). "Both TAP1 and TAP2 overexpression in breast cancer might be an indicator of an aggressive breast tumor." (PMID 29091951, 2017). "Notably, downregulation of TAP1 and TAP2 has been described as an immune evasion mechanism in gliomas, a subtype of breast cancer, and murine fibroblasts after oncogenic transformation, similar to the downregulation of β2-Microglobulin in diffuse large B cell lymphomas and colorectal carcinomas." (PMID 35681710, 2022). "Because TAP1 and TAP2 are both located on chromosome 6 and are under the control of IFN-γ to form a heterodimer in the endoplasmic reticulum membrane, we asked whether the expression of these subunits correlated with each other in the breast cancer specimens." (PMID 29091951, 2017). "Our results indicate that these strategies may not be necessary in advanced stages and higher grades of breast cancer, which already display the TAP1 and TAP2 subunits." (PMID 29091951, 2017).
type 1 diabetes (6 papers, 2007 to 2021). "Studies have found TAP2 to be associated with various immune-related disorders, including autoimmune thyroiditis and type 1 diabetes, and pulmonary tuberculosis in Iranian populations." (PMID 34669738, 2021). "Of the remaining five genes, three [MICA, NCR3, and TAP2] have been previously associated with type 1 diabetes, while APOM and HLA-DRB5 have been associated with RA." (PMID 32245788, 2020). "(III) Markers related to diseases other than cancer include WASF2, LCP2 and FYB (Wiscott-Aldrich syndrome, all up) and TAP2 (up, polymorphisms in this gene are implicated in type 1 diabetes." (PMID 19455236, 2007). "Several reports have described genetic associations of TAP1 and TAP2 polymorphisms with autoimmune/inflammatory diseases including systemic lupus erythematosus, hypersensitivity pneumonitis, vitiligo, Graves’ disease, type I diabetes, systemic sclerosis, and ankylosing spondylitis." (PMID 31732831, 2020). "For example, certain polymorphisms of the transporter associated with antigen processing (TAP1 and TAP2) and the immunoproteasome subunits LMP2 and LMP7, both involved in MHCI antigen presentation, have been linked to type 1 diabetes (T1D) by genetic association studies." (PMID 27534821, 2016).
viral infection (6 papers, 2005 to 2024). "Changes in the helical conformation of porcine SLA‐I and TAP2 gene are related to viral infection and inflammation." (PMID 38720469, 2024). "However, carriers of the p.Ala565Thr mutant allele are high producers of TAP-2, suggesting that the protein is more stable, as mRNA and protein levels were not affected by the viral infection." (PMID 36619767, 2022). "We hypothesize that over-expression of transporters associated with antigen processing (TAP1 and TAP2), components of the major histocompatibility complex (MHC) class I antigen-processing pathway, enhances antigen-specific cytotoxic activity in response to viral infection." (PMID 16389301, 2005). "Patients with inherited CD8, TAP1, TAP2, TAPASIN, or β2-microglobulin deficiencies, all of whom have low levels of HLA-I in all cell types tested and low counts of blood CD8+ T cells, are not prone to viral infections either." (PMID 36736301, 2023).
COVID-19 (5 papers, 2022 to 2025). A disease caused by infection with severe acute respiratory syndrome coronavirus 2. "The intersection of the top-ranked genes in the two diseases identified CR1 and TAP2 as shared hub genes, suggesting their potential role in linking COVID-19 and SS-KCS." (PMID 40149556, 2025). "After a multifaceted evaluation using four mainstream machine-learning diagnostic predictors, the most accurate and sensitive random forest model identified CR1 and TAP2 as the common hub genes of COVID-19 and SS-KCS." (PMID 40149556, 2025). "C Expression patterns varied across disease severity levels: CR1 showed the highest expression in severe COVID-19 cases and the lowest in healthy individuals, while TAP2 was most highly expressed in healthy samples and lowest in mild COVID-19 cases." (PMID 40149556, 2025). "This further supports its involvement in immune modulation and highlights the potential role of TAP2 in both COVID-19 and SS-KCS." (PMID 40149556, 2025). "Moreover, while we confirmed the association between immune cell proportions and hub genes, we did not investigate the specific mechanisms through which CR1 and TAP2 mediate the link between COVID-19 and SS-KCS, warranting further investigation." (PMID 40149556, 2025). "Interestingly, an upregulation of many APM components, particularly TAP2, was found in TMPRSS2high cells and COVID-19 PBMNCs." (PMID 40055791, 2025). "Furthermore, high viral load in SARS-CoV-2 infection activates the expression of TAP2 and other immunoproteasome components in lungs of COVID-19 patients and may result in worsening of disease prognosis." (PMID 36143338, 2022). "Together with the clinical information on COVID-19, the expression of CR1 and TAP2 was significantly correlated with the status and severity of COVID-19." (PMID 40149556, 2025). "To further elucidate the role of hub genes in the interaction between COVID-19 and SS-KCS, we performed a Pearson correlation analysis to assess the correlation between CR1, TAP2, and various immune cells." (PMID 40149556, 2025). "Regarding the status and severity of COVID-19, CR1 was significantly upregulated in COVID-19 patients, whereas TAP2 exhibited higher expression in healthy individuals." (PMID 40149556, 2025). "Further analysis of gene importance across the four models revealed that the top four hub genes in COVID-19 were CR1, TNFRSF10C, TAP2, and TGFBI, while the top four hub genes in SS-KCS were CR1, IL13, TAP2, and IL1R2." (PMID 40149556, 2025). "There was a positive correlation between COVID-19-related protein RPS6 and TAP2." (PMID 35720320, 2022).
ovarian carcinoma (5 papers, 2013 to 2021). A malignant neoplasm originating from the surface ovarian epithelium. "This study investigated the relationship of the five ABC transporters ABCA1, ABCB1, ABCB3 (also known as TAP2), ABCC2 and ABCG2 with ovarian cancer chemoresistance and outcome." (PMID 35582032, 2021). "Other ABC transporters, including ABCB3 (TAP2), ABCC1 (MRP1), ABCC2 (MRP2, cMOAT), and ABCC3 (MRP3), have been shown to be involved in ovarian cancer chemoresistance." (PMID 24124770, 2013).
asthma (4 papers, 2017 to 2022). "Recently, Ma and colleagues identified three cis-regulatory eSNPS for TAP2 as candidates for childhood-onset asthma risk (rs9267798, rs4148882 and rs241456)." (PMID 34669738, 2021). "Based on multiple lines of evidence, we highlighted 31 genes including PSMB9 and TAP2 with multiple eSNPs as childhood-onset asthma-associated causative candidates." (PMID 32867763, 2020). "We noticed that the eSNP of rs4148882 has cis-regulatory roles in influencing both PSMB9 and TAP2 expression, indicating that these two genes may have convergent effects on childhood-onset asthma susceptibility, which is in line with the findings in our GeneMANIA-based PPI network analysis." (PMID 32867763, 2020). "The genes of HLA-DRB5, HLA-DQA1, HLA-DPB1, CTSW, PSMB9, and TAP2 have the most number of edges with both predicted genes and childhood-onset asthma-related genes." (PMID 32867763, 2020). "Based on comprehensive genomics analyses, we found 31 genes with multiple eSNPs to be convincing candidates for childhood-onset asthma risk; such as, PSMB9 (cis-rs4148882 and cis-rs2071534) and TAP2 (cis-rs9267798, cis-rs4148882, cis-rs241456, and trans-10,447,456)." (PMID 32867763, 2020). "Three distinct transcriptional asthma phenotypes (TAPs) were identified that had similarities to previously defined sputum inflammatory phenotypes of eosinophilic (TAP1), neutrophilic (TAP2), and paucigranulocytic (TAP3) asthma." (PMID 29018800, 2017).
colon cancer (4 papers, 2012 to 2025). "Besides human DCs, we used T2 cells, TAP2-deficient lymphoblastoid cells which express low levels of HLA-A02*01 at cell surface due to lack of endogenously bound peptides, and the epithelial colon cancer cell line SW948." (PMID 32164343, 2020). "Conversely, protective genes such as PAEP, TAP2, CXCL10, and IRF1 were notably down-regulated in colon cancer cells." (PMID 40959081, 2025).
glioma (4 papers, 2019 to 2022). A benign or malignant brain and spinal cord tumor that arises from glial cells (astrocytes, oligodendrocytes, ependymal cells). "We explored the regulation of SAHA on constitutive expression of MHC-I, TAP1, TAP2, LMP2 and LMP7 proteins in glioma cells." (PMID 31737100, 2019).
Immunodeficiency (4 papers, 2020 to 2022). Failure of the immune system to protect the body adequately from infection, due to the absence or insufficiency of some component process or substance. "In KEGG, genes associated with immune disease and system include HLA-DQA1, HIST1H2BL, HIST1H2AL, C2, CFB, HSPA1A, TAP2, HIST1H3Jand ATP6V1G2." (PMID 34367251, 2021). "Finally, regarding other molecules of interest that we identified, another interesting point was the positive effect of curcumin treatment on the decrease in HA12 and TAP2 that we previously observed in relation to the immunodeficiency produced by M5-T1 tumor cells." (PMID 33207594, 2020). "Therefore, it is reasonable to postulate that the dysregulation of PAK2, TAP2, and PLCL1 genes is likely to elicit autoimmune reactions by altering antigen processing and presentation, T cell receptor signaling, and immunodeficiency pathways." (PMID 35783297, 2022). "TAP2:p.Arg252ThrfsTer11, which results in the truncation in the ABC transporter transmembrane domain making it non-functional, is likely to cause combined immunodeficiency with low CD8." (PMID 33481921, 2021).
pulmonary tuberculosis (4 papers, 2012 to 2021). A bacterial infection that affects the lungs and is caused by Mycobacterium tuberculosis. "Many genetic variants in TAP2 gene have been reported to contribute susceptibility to pulmonary tuberculosis, diffuse panbronchiolitis, aspirin exacerbated respiratory disease, and idiopathic bronchiectasis." (PMID 32867763, 2020). "In 1997, Rajalingam R and colleagues first reported a statistical association between alleles in TAP2 region with pulmonary tuberculosis and tuberculoid leprosy susceptibility in the North India populations." (PMID 22427944, 2012). "Tuberculosis (TB) is a common infectious disease, and the present study aims to explore the associations of single nucleotide polymorphisms (SNPs) at rs1135216 and rs1057141 of transporter-associated antigen processing (TAP1) and rs2228396 of TAP2 with pulmonary tuberculosis (PTB) risk." (PMID 33736739, 2021).
Type I bare lymphocyte syndrome (4 papers, 2014 to 2025). "Autosomal recessive mutations in TAP1, TAP2, TAPBP, or B2M, are associated with major histocompatibility complex (MHC) class I deficiency." (PMID 41298860, 2025). "One disease, Bare lymphocyte syndrome type I, has a full intersection with the TAP complex, because three proteins (TAP1, TAP2 and TAPBP) are the proteins causing the disease and the members of the PC at the same time." (PMID 32591566, 2020). "Indeed, one participant had a CNV spanning three recessive immune genes PSMB8, TAP1, and TAP2, which are associated with autoinflammation, lipodystrophy, dermatosis syndrome (PSMB8), and type I bare lymphocyte syndrome (TAP1 and TAP2)." (PMID 24672537, 2014).
Arthritis (3 papers, 2020 to 2024). Inflammation of a joint. "Interestingly, in our study, TAP2 was also effective in reducing the progression of MIA-induced arthritis in rats." (PMID 33060735, 2020). "In conclusion, TAP2 could effectively attenuate MIA-induced arthritis in rats by blocking TLR4 and its successive inflammatory cytokines and MMP13." (PMID 33060735, 2020).
esophageal adenocarcinoma (3 papers, 2019 to 2024). A malignant tumor with glandular differentiation arising predominantly from Barrett mucosa in the lower third of the esophagus. "In esophageal adenocarcinoma cells, reduced levels of miR125a-5p to increase expression of TAP2 through directly targeting TAP2 3’ UTR, which is associated with suppression of anti-tumor immune response and poor outcomes of patients." (PMID 30691465, 2019). "miR-125a-5p was shown to regulate TAP2 in esophageal adenocarcinoma cells." (PMID 38539461, 2024).
gastric cancer (3 papers, 2021 to 2025). A primary or metastatic malignant neoplasm involving the stomach. "TAP1 and TAP2 expressions were also higher in EBV-associated gastric carcinoma samples than in normal control tissues or other gastric carcinoma subtypes." (PMID 36619767, 2022).
primary immunodeficiency (3 papers, 2020 to 2022). "TAP2 is associated with Antigen processing and presentation, and primary immunodeficiency, and PLCL1 in GABAergic synapse, and T cell receptor signaling pathway." (PMID 35783297, 2022). "An equally high overrepresentation (OVF = 20.83, q-value = 2.38 × 10−6) was determined for the “magenta” module that was enriched in genes that control primary immunodeficiency, including ADA, CD19, CD79A, IGLL1, TAP1, TAP2, TNFRSF13C, and ZAP70." (PMID 32873298, 2020).
tuberculosis (3 papers, 2021). A chronic, recurrent infection caused by the bacterium Mycobacterium tuberculosis. "Among TAP2 SNPs only one, rs4148876, was associated with tuberculosis and with several types of cancer, and TAP2 transcript expression was higher in cancer than in normal tissue, which was also associated with patient survival." (PMID 33920176, 2021).
agranulocytosis (2 papers, 2017 to 2020). "Rs2228391, which is located in exon 4 of the TAP2 gene, was previously shown to be associated with ATD-induced agranulocytosis in Chinese patients from Taiwan21." (PMID 28931918, 2017).